HOXA13 (homeobox A13)
Diseases named in the same sentence as HOXA13 in open-access papers (continued):
Sharing a sentence is not in itself a finding about the gene and the disease.
tumor (continued). "Six MLLT1-mutant tumours and six randomly selected MLLT1-wild-type FHWTs were analysed by quantitative reverse transcription PCR, which confirmed increased expression of both HOXA13 and HOTTIP in MLLT1-mutant tumours." (PMID 26635203, 2015). "MEG3, HOXA13, and KCNQ1OT1 were all overexpressed in HCC tumor tissues (P = 0.001, P < 0.001, and P = 0.004, resp)." (PMID 26136615, 2015). "As a crucial tumor promoter, HOTTIP promotes cell proliferation, invasion, and chemoresistance by modulating HOXA13." (PMID 25889214, 2015). "N6-methyladenosine (m6A) RNA binding protein YTHDC2 can directly inhibit SLC7A11 on the one hand, and destabilize the mRNA of transcription factor HOXA13 in an m6A dependent manner, thereby inhibiting HOXA13-mediated transcription of SLC3A2, thereby damaging tumor growth." (PMID 37005430, 2023). "Considering the regulation of the FAK/Src axis in tumor progression, we speculated that the FAK/Src axis played an important role in the biological effects of HOXA13." (PMID 35197128, 2022). "In the almost all of cases, HoxA13 and HoxB13 were expressed in the nucleus of tumor cells, with concomitant non-specific cytoplasmic staining." (PMID 31882852, 2019). "For this phenomenon, we hypothesized that, tumor-bearing mice may be tolerated in response to the intermittent administration of chemotherapy, and the expression of HOTTIP and HOXA13 in the tumors showed a corresponding increase." (PMID 29367594, 2018). "It has been reported that HOXA13 may promote GBM progression through activation of Wnt/beta-catenin and TGF-β signaling pathway, whereas downregulation of HOXA13 may suppress GBM cell invasion and decrease tumor growth." (PMID 31531345, 2019). "The coordinated dysregulation of HOTTIP and HOXA13 in different tumor types supports their strong interaction and involvement in general mechanisms of neoplastic transformation, regardless of specific tumor phenotypes." (PMID 31137568, 2019). "Additionally, HOXA13 and KCNQ1OT1 were upregulated in HCC tumor tissues." (PMID 26136615, 2015). "Therefore, HOXA13 may activate TGF-β signaling by interacting with the MH2 domain of SMAD2/3 to regulate the nucleus-cytoplasm distribution of phosphorylated-SMAD2/3 and promote tumor progression." (PMID 26356815, 2015). "Our data showed the absence of expression of HOXA13, HOXB13, HOXC13 and HOXD13 in the normal mucosa, a slight increase in expression in the transitional mucosa, up to in many cases over-expressed in the tumor." (PMID 30541551, 2018).
infection (1 paper, 2015). The state of being infected such as from the introduction of a foreign agent such as serum, vaccine, antigenic substance or organism. "After 48 h of infection, HOXA13 protein expression levels in U87, U87-EGFRvIII, LN229, and U251 were decreased, and HOXA13 expression was mainly restricted to the nuclear protein fraction." (PMID 26356815, 2015).
HOXA13 also shares sentences with these, for which no sentence is quoted: synpolydactyly (3 papers); thyroid cancer (3); bladder (2); developmental delay (2); adrenal tumour (1); anorectal malformation (1); astrocytoma (1); atrial fibrillation (1); basal cell carcinoma (1); chronic heart failure (1); chronic myeloid leukemia (1); cleidocranial dysplasia (1); cryptorchidism (1); fibroid (1); genetic diseases (1); gestational diabetes (1); Guttmacher syndrome (1); hematologic malignancies (1); hyperlipidemia (1); insulinoma (1); Intellectual disability (1); laryngeal squamous cell carcinoma (1); liver cirrhosis (1); melanoma (1); Micropenis (1); MRKH syndrome (1); Myhre syndrome (1); nail-patella syndrome (1); of Synovial Sarcoma (1); oligodendroglioma (1).
A further 9 diseases each share a sentence with HOXA13 in 1 paper.